TNF (tumor necrosis factor)
Diseases named in the same sentence as TNF in open-access papers (continued):
Sharing a sentence is not in itself a finding about the gene and the disease.
infection (continued). "The TNF-α expression tended to rise with infection time, but showed a minor reduction at 6 h after infection and subsequently surged again, peaking at 12 h." (PMID 35812882, 2022). "As is known, in brain tissue, microglia act as the sole resident immune cell, thus, we surmised that the high level of TNF-α was produced by microglia upon AC infection." (PMID 33683530, 2022). "At 48 h, infection with M. s_Rv1515c led to significant (p < 0.001) reduction in IL-6 (5-fold decrease), reduction (p < 0.05) in IL-12 and TNF-α level, as compared to M. s_Vc." (PMID 35813825, 2022). "Mammalian cells can induce the eif2 signaling following infection by bacterial pathogens, and the transcription of cytokines including TNFα is regulated by eif2 signaling." (PMID 35742911, 2022). "At 24 h post infection, we observed a significant decrease in the levels of TNF mRNAs in infected cells treated with VS-X4 or H-151, compared to DMSO or AMX treated cells, in both A549-ACE2 and Calu-3 cells." (PMID 35022513, 2022). "This response is attributed to cytokines such as tumor necrosis factor, although infection is more likely." (PMID 35983308, 2022). "BALB/c mice were infected with 105 TCID50 maVie16 and treated intraperitoneally on days 1 and 3 post infection (p.i.)with a mix of 500 μg anti-IFNγ and anti-TNF or with isotype control antibody." (PMID 35023830, 2022). "We found that a protective response was associated with proliferating, antigen-specific IFN-γ+ TNF+ CD4+ T cell cells, which were prominent in patients who cleared the infection." (PMID 36439147, 2022). "At 4 weeks post-infection, TNF-α gene transcription was elevated approximately 1.6-fold in the high-dose group with lower levels detected in the medium- and low-dose groups, while at 7 weeks, levels were low in all groups." (PMID 36051240, 2022). "CRP assists with the host response to infection, including phagocytosis, complement pathway, nitric oxide (NO) release, and cytokines production, especially interleukin-6 and tumor necrosis factor-α." (PMID 35154932, 2022). "It reduces the production of pro-inflammatory factors such as interleukin (IL)-1β and tumor necrosis factor (TNF)-α and increases the production of the anti-inflammatory cytokine IL-10, which results in immunosuppression and worsening of infection." (PMID 36556017, 2022). "Similar to the mtDNA levels, the levels of PICs (IL-6, IL-1β, and TNF-α) and IL-10 were consistently downregulated in patients with OmicronS infection." (PMID 36230930, 2022). "The cytokines IFN-γ, TNF-α, IL-10, and IL-17 were also measured in the homogenate of the heart after 28 days of infection." (PMID 35097133, 2022). "During infection, there is macrophage activation and cytokine production, tumor necrosis factor-alpha (TNFα) and interleukin 12 (IL-12) are significant protective cytokines." (PMID 36671276, 2022). "Expression profiles of TNF-α signaling-related genes at 24 and 36 h after infection were visualized on a KEGG pathway diagram." (PMID 35846740, 2022). "Cytokine gene expression in Caco-2 and RAW 294.7 cells in response to ST infection was quantified, with IL-2, IL-6, and TNF-α having been investigated." (PMID 35438052, 2022). "In an inflammatory environment, the infection of susceptible C57BL/6 mice revealed production of IL-12 and TNF-α considerably higher than in BALB/c mice." (PMID 36566237, 2022). "Zinc supplementation studies have shown decreased oxidative stress due to its participation in free radical scavenging and pro-inflammatory markers levels such as IL-1, IL-6 and TNFα, even during infection." (PMID 36138753, 2022). "Randomized controlled trials (RCTs) and observational studies comparing anti-TNF-α de-escalation strategies with standard dosing among patients with inflammatory conditions, that report on infections, skin manifestations, or both, were included." (PMID 35625771, 2022).
infection (continued). "Infection pathway-related molecules, for example IL-6, TNF, TLR4 and prostaglandins were commonly reported across these studies." (PMID 35379367, 2022). "TNF-α can recruit monocytes, granulocytes and other innate immune cells to the location of infection and helps to form tuberculous granulomas in the infected tissues, which is beneficial to prevent the dissemination of TB bacteria in the body." (PMID 36619740, 2022). "In the case of severe inflammation or infection, M1 macrophages release TNF-α, IL-1β, IL-12, and IL-23 to participate in the immune response to stimuli." (PMID 36362965, 2022). "CRP is increased in response to IL-6, IL-1β and TNF-α activation during infection and systemic inflammation." (PMID 35958594, 2022). "Th17 lymphocytes stimulate epithelial cells and stromal cells to release IL-8, which is a chemo attractant for neutrophils, and Th17 lymphocytes also induces the production of TNF-α from macrophages and neutrophils cells at the site of infection." (PMID 36057049, 2022). "Oral-gut pathogen infection has long-term effects to produce ROS or stimulate inflammatory cytokines, such as interleukin (IL)-1β, IL-6, IL-8, and tumor necrosis factor-α (TNF-α)." (PMID 35814712, 2022). "In dairy cows, the increase in TNF-a along with other pro-inflammatory cytokines is important for the host’s immune response to infection and can therefore inhibit the expression of milk proteins." (PMID 36356101, 2022). "In another study, bone marrow (BM)MCs co-cultured with C. albicans produced TNF-α, IL-6, IL-13, and IL-4, and increased the crawling ability of PMφs to the site of infection." (PMID 35628223, 2022). "It was shown that the expression of NFkB, both subunits, as well as TNFα was significantly increased in the initial phase of infection and persists (or even increases) despite recovery." (PMID 35456059, 2022). "Infections were observed in 20% of patients on anti-TNF and 17% on VDZ after 1 year of follow-up (p = 0.54)." (PMID 35956040, 2022). "We analyzed IL-6 and TNF transcript level, as well as two other ARE-containing RNAs, encoding CXCL8 and COX-2 which were elevated after infection with SARS-CoV-2 and OC43." (PMID 35998203, 2022). "We then measured the phosphorylation of NF-κB by TNF-α activation by Western blot, where we observed that Bpm inhibits NF-κB activation despite TNF-α stimulation post infection." (PMID 35984745, 2022). "In the inflammatory response against tissue injury and infection, excessive inflammatory cytokines such as IL‐6 and TNF‐α are activated and play a crucial part in the progression of ALI." (PMID 36514748, 2022). "Following infection with opportunistic pathogens, cytokine expression of IL-1β, IL-6, and TNF-α in the mucosa and serum increased significantly (P < 0.05), which resulted in decreased immunity." (PMID 35769317, 2022). "Our results showed that both TNF-α, and IL-1β were down-regulated by EbSe-Ag+, contributing to host defense during infection." (PMID 35958130, 2022). "Last, mice with stable, controlled infection treated with anti-TNF Abs began dying as soon as 2 weeks after treatment, and treated mice exhibited significantly higher extrapulmonary fungal burdens." (PMID 36166305, 2022). "Measures such as promastigote growth curves, macrophage infection profiles, inflammatory mediators’ production (TNF-α, IL-6 and NO) and serine proteases expression (subtilisins and OPB) showed heterogenic profiles of these clinical isolates." (PMID 35531337, 2022). "Parasitic infections often lead to the upregulation of TNF-α, which was observed in cases infected with various parasites including A. cantonensis, Leishmania braziliensis, Plasmodium and Toxoplasma gondii." (PMID 33683530, 2022). "Another study showed that F. nucleatum significantly promoted the secretion of TNF-α and IL-1β, while S. gordonii promoted the secretion of TNF-α, IL-6, IL-8, and IL-1β after 24 h of infection." (PMID 35573793, 2022).
infection (continued). "One patient in the anti-TNF-α group exhibited infection by C. albicans, with others showing infection by C. albicans, C. krusei and C. dubliniensis." (PMID 35323234, 2022). "In this study, IL-27 was responsible for reducing the levels of TNF and IFNγ required for parasite control, therefore favoring infection." (PMID 35384718, 2022). "Mice that received a poor protein diet succumbed earlier to the infection, which was associated to an impaired production of IFN-γ, TNF-α and NO synthase." (PMID 36678397, 2022). "TNF-α is a marker of M1 macrophage, which elicits rapid proinflammatory responses to infection and tissue damages." (PMID 36578570, 2022). "According to functional analysis, these hub genes are mainly involved in the TNF, AGE-RAGE, IL-17, and MAPK pathways, which are linked to the host inflammatory response to infection and viral replication." (PMID 36422594, 2022). "The recruitment of CD8+ T cells to tissue typically occurs due to pathogenic infection and contributes to IFN-γ and TNF-α production." (PMID 36466642, 2022). "Both Th1 (IFN-γ, TNF-α, IL-12) and Th2 (IL-4 and IL-10) types of cytokines were differentially upregulated during the early stage of infection; however, the Th1 cytokines exhibited stronger activation before 8 hpi compared to those of the Th2 cytokines." (PMID 35215986, 2022). "It is well-known that TNF-α and IL-6 are classic proinflammatory cytokines functioning in many biological processes such as inflammation, infection, and wound healing." (PMID 36090347, 2022). "Secondly, infection with SARS-COV-2 significantly increased the level of TNF-α and IL-6, suggesting that activated microglia lead to neuroinflammation." (PMID 36353605, 2022). "The TNF-α secretion is likewise impaired following infection with the ΔbepD and the full Bep deletion mutant ΔbepA-I at 6 hpi, but significantly increased in cells infected with the ΔvirD4 mutant." (PMID 35910598, 2022). "Activated macrophages release tumor necrosis factor alpha (TNF-α) which increases recruitment of monocytes to the site of infection and surrounding tissues." (PMID 35170334, 2022). "Results showed that the expression of TNF-α was significantly induced in the liver of chickens infected with the wild-type strain at 3 and 5 days post-infection." (PMID 35694286, 2022). "The levels of IL-6 and TNF-α in the model group were significantly increased on both day 4 and day 7 post-infection when compared with the control group." (PMID 36452894, 2022). "We found either Compound B treatment or oxsr1a knockdown results in localised increased TNFα production at sites of infection." (PMID 35545295, 2022). "In responding to infection, T lymphocytes, monocytes, and neutrophils are recruited to infection sites and secrete various cytokines, such as TNF-α, IL-1, and IL-6." (PMID 36238276, 2022). "The results from the ZIKV-infected astrocytoma cells were very similar to the results observed following CHIKV infection, with both CXCL10 and TNF-α robustly induced following infection." (PMID 35746681, 2022). "In the case of SARS-CoV-2, an increase in the concentration of inflammatory cytokines such as IL-1β, IL-2, IL-6, IL-7 and TNF-α comes to the fore, along with the rise in IL-4 and IL-10 concentrations in a later stage of infection." (PMID 36294388, 2022). "Accumulating evidence suggests that IL-1β and TNF-α are typical pro-inflammatory cytokines that are rapidly increased when tissue injury or infection." (PMID 36118767, 2022). "In the early stage of infection, a variety of inflammatory cells are recruited and activated to release large amounts of inflammatory cytokines and chemokines, such as TNF-α and IL-1β, which are rapidly secreted and reach to the peak within a few hours." (PMID 35197984, 2022). "The plasma levels of IL-6, IL-1β, and TNF-α were higher in the untreated group than in the mock group on days 1, 3, and 5 post-infection." (PMID 36569095, 2022).
infection (continued). "In contrast, AMΦ from BALB/c mice showed higher production of NO, TNF-α, and IL-10 after 7 days of intratracheal infection." (PMID 36520787, 2022). "We observed moderately decreased TNFα secretion in C3ar-/- BMDMs infected with Hc at 2h post-infection, but this effect was diminished at 6h post-infection." (PMID 36174103, 2022). "At 24 h post infection, there was increased expression of TNF-α, IL-1β, IL-6, and IL-12 in the lungs of mice infected with the ΔEfb strain compared to those infected with the Newman and ΔEfb + Flag − Efb strains." (PMID 36123338, 2022). "The concentration of cytokines in NHBE cells in response to infection in our study indicated that the expression of the proinflammatory cytokines IL-1β, IL-6, and TNF-α was induced by H7N9 infection, but reduced by pdmH1N1 in the early stage of infection." (PMID 35269402, 2022). "Our results showed that the expression of the pro-inflammatory cytokine gene TNF-α was upregulated in the THP-1 monocytic cell line after infection with all the Aeromonas strains as also occurred for the THP-1 after V. vulnificus infection." (PMID 35874671, 2022). "Meanwhile, QKI deficient RAW 264.7 cells showed increased secretion of pro-inflammatory cytokines, such as TNF-α, IL-6, IL-1β, and decreased secretion of IL-10, post-infection." (PMID 36088389, 2022). "TNFα is rapidly released and is one of the most abundant mediators of inflammation in the peripheral blood after infection or exposure to LPS." (PMID 35109859, 2022). "Patients in the low Sirt3 group had higher ScvO2, lactate, APACHE II score, SOFA score, longer ICU stays, and worse indicators of inflammation (TNF-α, IL-6) and infection (PCT) than those in the high Sirt3 group (P < 0.05)." (PMID 35729330, 2022). "Although the role of TNF in infection is beneficial, it is necessary to strictly regulate the production of TNF to protect the host from the harmful activity of TNF." (PMID 35327113, 2022). "Only one study showed that the IR of serious infection in patients who were 75 years or older and received TNF inhibitors was 8.3/100 PY." (PMID 35689250, 2022). "We specifically show that different possible inflammatory states in BV are either associated with persistence of HR-HPV infection (i.e., IL-1β/IP-10) or the progression of infection to precancer (i.e., TNF-α/MIP-1β)." (PMID 35017496, 2022). "Regarding cDC1, the frequency of cells producing IL-10 and/or TGF-β1 reduced significantly, although with a negligible percentage of cells producing TNF-α after infection." (PMID 35720410, 2022). "Long MY claimed that autologous blood transfusion can increase the levels of TNF-α and complement C3 in patients, thereby enhancing their immunity against infection." (PMID 34979913, 2022). "TNF- plays an important role in the physiological function, immune regulation and anti-infection process of the body." (PMID 35401167, 2022). "We found that HAdV26 infection of human epithelial cells triggers the expression of pro-inflammatory cytokines, namely IL-6, IL-8, IL-1β, and TNF-α." (PMID 35458402, 2022). "We also observed that the level of IFN-γ and TNF-α in NK cells was decreased, more especially in symptomatic patients with ongoing infection, as previously observed in individuals with severe disease." (PMID 35911747, 2022). "The results of qRT‐PCR showed that TNF‐α, a marker gene of M1 macrophages, began to increase significantly at 30 days after infection." (PMID 36169259, 2022). "A subset of the significantly changed targets, genes, and miRNAs was connected via the TNF and cell cycle signaling pathways in response to infection and the cell cycle signaling pathway alone in response to infection plus SP-A2 (1A0) protein rescue." (PMID 35844510, 2022). "In this study, we observed that upon phagocytosis of L. corymbifera, human monocytes released IL-1β during the first hours of infection, while TNF-α and IL-6 were significantly released in later stages of the infection." (PMID 36311802, 2022).
infection (continued). "The results confirmed previous flow cytometry data obtained using CBA kit, which showed an early increase in TNF-α in the immunized groups and significantly higher levels of IL-6 in the group immunized with the hybrid within the first six hours of infection." (PMID 36477013, 2022). "Neutrophil accumulation is driven by TNF and IL-8 production by macrophages and alveolar epithelial cells, and this subset congregates within murine lungs following infection with both S and R morphotypes." (PMID 35308378, 2022). "TNF-α, produced from stimulated mononuclear macrophagus, involved in infection preventions, and promoting inflammation cell differentiation." (PMID 35499101, 2022). "Especially during the infection of virus, bacteria or parasites, TNF-α can activate CD4 T cells, enhance the kill capacity of macrophage, induce death of infected cells." (PMID 35491409, 2022). "In mice suffering from acute lung injury caused by lipopolysaccharide (LPS)-induced infection, a one-off CBD dose (20 mg/kg) administered prior to infection decreased the production of pro-inflammatory TNF, IL-6, MCP-1, and MIP-2." (PMID 35891472, 2022). "Macrophage activation is an important strategy to prevent infection, and it is stimulated by cytokines such as interferon γ, IL-1β, and TNF-α or by certain bacterial extracellular components such as LPS and external chemicals." (PMID 35723329, 2022). "Along with this, the expression of proinflammatory cytokines IL‐6 and TNFα was elevated in aged PBMCs upon infection." (PMID 35313074, 2022). "In the early stages of infection, carbohydrate moieties associated with soluble VSG released by circulating parasites induce TNF production by activated macrophages leading to trypanosome clearance." (PMID 35634275, 2022). "In our study, infection with B.1.351 elevated the levels of IFN-γ, TNF-α, IL-13, and IL-10, whereas infection with GD108 elevated the level of IL-17 in macaques." (PMID 36069561, 2022). "During early in vivo infection in mice, AMs upregulate a Nrf-dependent transcriptional program that limits IL-1β and TNF production to impair the control of Mtb33." (PMID 35173157, 2022). "Lastly, in response to M. bovis intramammary infection over a period of several days, initial elevations of TNF-α, IL-1β, and IFN-γ were observed between 90 and 102 h post infection, suggesting the late onset of these factors depend on causative pathogens." (PMID 35335696, 2022). "TNF-α, IL-1, and IL-6 are pro-inflammatory cytokines essential for initiating an inflammatory response to infection." (PMID 35356501, 2022). "Although ghB (~−0.25 log10) treatment downregulated the expression, ghC (~0.39 log10) treatment upregulated TNF-α mRNA expression 6 h post-infection." (PMID 35328462, 2022). "While IL6 levels were lower in SARS-CoV-2+ children as compared to adult patients, the expression of other pro-inflammatory cytokines such as IFNγ and TNFα directly correlated with early age infection and symptoms." (PMID 35626859, 2022). "It has been demonstrated that MIF plays a critical protective role during acute T. cruzi infection, by inducing the production of several pro-inflammatory cytokines, including IL-12, IL-18, TNF, IL-1β, and IFNγ, during the early phase of infection." (PMID 35464430, 2022). "The tubercle bacillus produces excessive tumor necrosis factor after infection and has extreme mitochondrial reactive oxygen species (ROS) through the mitochondrial-endoplasmic reticulum circuit, triggering the programmed necrosis of macrophages." (PMID 35373713, 2022). "Cytokines including IL-1β, IL-6, IL-12 p40, IP-10, IFN-γ, and TNF-α were increased in S. enteritidis-infected mice at 4 days post-infection." (PMID 35222370, 2022). "Of note, we demonstrated that si‐Hsf1 counteracted melatonin‐mediated suppressive effects on the levels of IL‐1β and TNF‐α in the serum and lung at 12 h post PmCQ2 infection." (PMID 35184395, 2022).